TRPC1 (transient receptor potential cation channel subfamily C member 1)
Diseases named in the same sentence as TRPC1 in open-access papers (continued):
Sharing a sentence is not in itself a finding about the gene and the disease.
glioma (continued). "Evidence that TRPC1 expression is essential for growth in vivo was assessed by injecting nude mice glioma cells ectopically expressing doxycycline-inducible shRNA targeting TRPC1." (PMID 32046188, 2020). "TRPC1 is required for PDGF- and EGF-mediated directional migration in glioma cells by cooperating with chloride channels that are activated by TRPC1-mediated Ca2+ influx." (PMID 29772843, 2018). "On the other hand TRP and ORAI1 channels functionally interact with other family of channels: a nice example is TRPC1 which is functionally related to ClC-3 in caveolar lipid rafts of glioma cells to promote EGF-induced chemotaxis." (PMID 24204345, 2013). "As concerning cancer cell migration, TRPC1 is expressed in several glioma cell lines, including D54, D65, GBM62, STTG1, U87, and U251 and in Grade IV malignant glioma patient tissue." (PMID 24204345, 2013). "Furthermore, TRPC1-mediated Ca2+ signaling can activate proteases and matrix metalloproteinases, facilitating the breakdown of the extracellular matrix and promoting glioma cell invasion." (PMID 37892239, 2023). "TRPC1 channels may affect glioma cell division mainly by regulating calcium signaling during cytokinesis." (PMID 35625048, 2022). "Among the eight final identified hub genes, higher expression levels of TRPC1, TRPC3, and TRPC5 were significantly associated with longer OS time in glioma, while higher expression levels of TRPC4, TRPC6, MCOLN1, MCOLN2, MCOLN3 were significantly associated with shorter OS time." (PMID 35625048, 2022). "The important role of TRPC1 in glioma cell division has been also confirmed in vivo through a shRNA knockdown approach on a flank GBM cell tumor model: TRPC1 downregulation led to a significant decrease in tumor size, most likely impairing calcium signaling during cytokinesis (late M-phase)." (PMID 33928077, 2021). "TRPC1 has also revealed a role in controlling glioma cell migration." (PMID 33928077, 2021). "The expression of TRPC1 promotes cytokinesis, proliferation and motility in glioma cells." (PMID 33096667, 2020). "TRPC1 is essential in glioma cell division, likely because of its regulatory effect on calcium signalling during cytokinesis, confirming it’s functional role in in the proliferation and migration of glioma cells." (PMID 33096667, 2020). "In migrating glioma cells TRPC1 and ClC-3 channels form a functional unit colocalized in caveolae." (PMID 27903970, 2017). "Interestingly TRPC1-mediated Ca2+ entry seems to colocalize with Chloride Channel ClC-3 in caveolar lipid rafts of glioma cells." (PMID 24204345, 2013). "Therefore the authors propose that Cl− channels (most likely ClC-3) are important downstream target of TRPC1 in glioma cells, coupling elevations in [Ca2+]i to the shape and volume changes associated with migrating cells." (PMID 24204345, 2013). "Interestingly, TRPC1 channels localize to the leading edge of migrating glioma cells where they co-localize with markers of caveolar lipid rafts." (PMID 24204345, 2013). "In glioma cells TRPC1 has been correlated with EGF-mediated directional migration." (PMID 24204345, 2013). "However, the role of TRPC1 in calcium dysregulation in gliomas remains incompletely understood." (PMID 41787243, 2026). "For instance, mRNA encoding TRPC1, TRPC6, TRPM7, TRPM8, TRPV4, and TRPML2 appeared up-regulated in GBM tumor specimens in comparison with normal tissues and their expression was found to increase with glioma tumor grade with the highest mRNA level found in GBM patient samples." (PMID 33928077, 2021). "Similar to TRPV4, TRPC1 is also increased in GBM patients and is involved in glioma cell proliferation and migration via regulating chemotaxis at the leading edge of migratory glioma cells." (PMID 36497413, 2022). "In previous reports, TRPC1, TRPC3, TRPC6, TRPML1, and TRPML2 were proven to play crucial roles in glioma progression." (PMID 35625048, 2022).
glioma (continued). "A previous study proved that the clinical value of TRPC1, TRPC6, TRPML1, and TRPML2 plays key roles in the diagnosis and prognosis of glioma patients." (PMID 35625048, 2022). "Glioma cell lines and surgical patient-derived tumors have revealed the expression of four TRP channels belonging to the TRP canonical subfamily that are TRPC1, TRPC3, TRPC5, and TRPC6." (PMID 33928077, 2021). "Consistent expression of TRPC1, TRPC3, TRPC5, and TRPC6 has been found in glioma cell lines and acute patient-derived tissues, which gives rise to small, nonvoltage-dependent cation currents and contributes to the resting conductance of glioma cells." (PMID 32963700, 2020). "TRPC1 channels have been shown to promote the release of pro-angiogenic factors, such as vascular endothelial growth factor (VEGF), from glioma cells, thus inducing endothelial cell proliferation and migration and leading to the formation of new blood vessels within the tumor microenvironment." (PMID 37892239, 2023). "The gene expression levels of TRPC1, TRPC3, and TRPC5 were significantly higher in low-grade glioma (LGG), while the levels of TRPC4, TRPC6, TRPM7, MCOLN1, MCOLN2, and MCOLN3 were significantly higher in high-grade glioma (HGG)." (PMID 35625048, 2022). "Interestingly, when stimulated with epidermal growth factor (EGF), TRPC1 relocated to the leading edge of migratory glioma cells (D54MG), suggesting a growth factor mediated role for TRPC1 in the migration of cancer cells." (PMID 33096667, 2020). "Furthermore, Bomben and Sontheimer have recently shown that silencing the expression of TRPC1, a member of the family of TRPC channels also involved in SOCE, inhibits the proliferation of D54MG glioma cells and in vivo tumor growth." (PMID 23578185, 2013). "Besides, the upregulation of TRPC1 and TRPC4 in IDH1mt‐R132H glioma cells." (PMID 39189437, 2024).
colon carcinoma (16 papers, 2016 to 2022). "It was also demonstrated that the SK3 potassium channel, in association with TRPC1 and Orai1 calcium channels, regulated colon cancer cell migration." (PMID 30884858, 2019). "They demonstrate that reducing the expression of TRPC1 inhibits migration of the HCT-116 colon cancer cell line by disrupting the complex formation of Ca2+-activated K+ channels (SK3), ORAI1, and TRPC1 in the lipid rafts." (PMID 32046188, 2020). "Further research revealed that DFMO treatment inhibits TRPC1 expression and eliminates the TRPC1 component of the store-operated currents in colon cancer cells." (PMID 32733237, 2020). "Taken together, these data suggest that SOCE induced by STIM1/Orai1/TRPC1 plays a role in SK3-dependent colon cancer cell migration." (PMID 27102434, 2016). "In the present study, we demonstrate that SOCE promotes migration of colon cancer cell following the formation of a lipid raft ion channel complex composed of TRPC1/Orai1 and SK3 channels." (PMID 27102434, 2016). "Furthermore, Cav-1 was reported to further contribute to STIM1/TRPC1/Orai1/SK3 complex formation in colon cancer." (PMID 35327543, 2022). "Although TRPC1 expression contributes to various tumor outcomes, its over expression is predominantly and most consistently correlated with poor cancer outcomes in lung, pancreatic, breast, glioblastoma multiforme, and colon cancers." (PMID 34199280, 2021). "For example, in human colon cancer, a complex interplay between TRPC1/Orai1 and STIM2 was identified, with TRPC1/Orai1 expression upregulation being associated with increased SOCE and Ca2+ store content, whereas STIM2 downregulation underlying Ca2+ store depletion and promoting apoptosis resistance." (PMID 32872338, 2020). "Whereas ORAI1 channels in normal cells are essentially inactivating, in colon cancer cells, perhaps the involvement of TRPC1 channels may contribute to sustain currents." (PMID 32733237, 2020). "This study demonstrates that the inhibition of the SOCE-dependent colon cancer cell migration trough SK3/TRPC1/Orai1 channel complex by the alkyl-lipid Ohmline may be a novel strategy to modulate Anti-EGFR mAb action in mCRC." (PMID 27102434, 2016). "In colon cancer cells, SK3 has been reported to colocalize not only with Orai1, but also with TRPC1 channels in lipid rafts." (PMID 33333945, 2020). "In the colon cancer cell HCT-116 line, activation of STIM1 by Ca2+ store depletion, using TG, results in the recruitment of Orai1 and TRPC1 into lipid raft domains containing SK3 channels." (PMID 30558192, 2018). "Recently, human colon cancer cells have been shown to present an increase of SOCE, related to an increase in TRPC1, Orai1, Orai2, Orai3 and STIM1 expressions." (PMID 27102434, 2016). "Similarly, colon cancer cell growth is driven by an interplay of SK3 and Orai1 which is further supported by STIM1 and TRPC1." (PMID 35327543, 2022). "In addition, TRPC1 and SK3 have been reported to play a role in the development of constitutive Ca2+ entry in and progression of colon cancer cells." (PMID 33333945, 2020). "In contrast, in colon cancer cells, SOCE is mediated by both ORAI1 and TRPC1 channels." (PMID 32733237, 2020). "Conversely, colon carcinoma cells showed mixed currents composed of enhanced ICRAC besides a nonselective Ca2+ current mediated by TRPC1." (PMID 31010205, 2019). "However, in colon cancer cells, SOCE depends on both ORAI1 and TRPC1 channels as reviewed next." (PMID 32733237, 2020). "Interestingly, SOCs in colon cancer cells, but not in normal cells, involve Na+ currents mediated by TRPC1 that form a channel complex with Orai1, thus allowing Na+ influx." (PMID 28903423, 2017).
glioblastoma (11 papers, 2014 to 2025). The most malignant astrocytic tumor (WHO grade IV). "Interestingly, the TRPC1 plasma membrane expression decreases upon PI3K inhibition in glioblastoma cells, which is associated with reduced chemotaxis and cell migration." (PMID 36230869, 2022). "Since then, TRPC1 has been characterized as an MS ion channel in root ganglion neurons, mice myocardial tissue, axons, glioblastoma cells, tumour-associated pancreatic stellate cells and bronchial epithelial cells." (PMID 33994356, 2021). "In a glioblastoma cell line, TRPC1 translocation to the plasma membrane depends on PI3K mediated transport, which results in Ca2+ entry, chemotaxis, and cell migration." (PMID 36230869, 2022). "In whole-cell patch-clamp recordings, 10 μM clemizole inhibits heteromeric TRPC1:C5 channels, and 50 μM clemizole partially inhibits riluzole-activated currents in the U-87 glioblastoma cell line." (PMID 29865154, 2018). "Also, in glioblastoma cells it was reported that S1P could activate the TRP channel TRPC1, leading to Ca2+ influx." (PMID 34054821, 2021). "In any case, it has been well established that both TRPC1 targeting to the leading edge of lamellipodia and its activation by S1P are essential in regulating PDGF-induced chemotaxis in U251 glioblastoma cells." (PMID 33928077, 2021). "Riluzole also activates overexpressed heteromeric TRPC1:C5 channels and endogenous TRPC5 channels in the U-87 glioblastoma cell line." (PMID 29865154, 2018). "Immunocytochemistry of TRPC1 in the absence of PDGF shows the channel is distributed across the plasma membrane of glioblastoma cells." (PMID 33994356, 2021).
hepatocellular carcinoma (11 papers, 2016 to 2023). A malignant tumor that arises from hepatocytes. "Transient receptor potential canonical 1 (TRPC1) down-regulation has previously been shown to be associated with hepatocellular carcinoma cell proliferation, and therefore TRPC1 may exist as a potential novel drug target." (PMID 27443843, 2016). "The upregulation of TRPC1 in the H4-IIE rat hepatoma cell line has been reported to result in notable augmentation of Ca2+ and Na+ influx in response to maintoxin." (PMID 37569884, 2023). "For instance, silencing TRPC1 is able to inhibit the proliferation of hepatocellular carcinoma cells, decrease the invasion, migration, and proliferation of thyroid cancer cells via reducing HIF-1α expression." (PMID 34642309, 2021). "TRPC1 and store-operated Ca2+ (SOC) entry have previously been associated with hepatocellular carcinoma cell proliferation." (PMID 27443843, 2016). "We monitored the real-time changes in proliferation of Huh7 hepatocellular carcinoma and A7r5 vascular smooth muscle cells with different initial seeding densities following transient receptor potential canonical 1 (TRPC1) silencing using xCELLigence system." (PMID 27981039, 2016). "Our previous observations demonstrated that TRPC1 silencing suppresses cell proliferation without affecting cell migration in Huh7 cells suggesting a regulatory role of TRPC1 in the proliferation of hepatocellular carcinoma cells." (PMID 27443843, 2016). "For this purpose, whole-transcriptome gene expression profiling was performed in TRPC1-silenced Huh7 hepatocellular carcinoma cells." (PMID 27443843, 2016). "Based on these data, among the hepatocellular carcinoma cell lines, Huh7 cells were chosen to further study the effects of cell seeding density on the proliferation of TRPC1-silenced cells." (PMID 27981039, 2016). "The aim of the study was to determine genes and processes associated with TRPC1 down-regulation and the resulting increase of SOC entry and decrease in hepatocellular carcinoma cell proliferation." (PMID 27443843, 2016). "Other studies showed expression of the TRPM7 channel in rat HSC-T6 hepatic stellate, RLC-18 and WIF-B hepatoma cells and of the TRPC1 channel in rat H4-IIE hepatoma cells." (PMID 26903865, 2016). "For this purpose, hepatocellular carcinoma cell proliferation-related genes were selected, and both correlation with TRPC1 and changes in relative expression were analysed." (PMID 27443843, 2016). "Among members of transient receptor potential (TRP) channels activated in response to oxidative stress, we here identify that redox-sensitive TRPV1, TRPC1, TRPM2, and TRPM7 channels underlie Ca2+ entry and downstream cellular damages induced by APAP in human hepatoma (HepG2) cells." (PMID 26903865, 2016). "Similarly, changes in cell cycle regulating genes in TRPC1-silenced cells indicate possible cell cycle arrest along with compensatory up-regulation of ERBB3 growth factor receptor—amongst others—to maintain hepatocellular carcinoma cell proliferation." (PMID 27443843, 2016). "Decreased TRPC1 may be compensated by increased expression of STIM1 that possibly takes part in the up-regulation of SOC entry in TRPC1-silenced hepatocellular carcinoma cells." (PMID 27443843, 2016). "Thus, the action of APAP via the modification target cysteine residues may at least in part account for the important roles of TRPV1 or TRPC1 in APAP-induced responses in human hepatoma cells." (PMID 26903865, 2016). "We have previously observed SOC entry to increase following TRPC1 silencing, suggesting a negative regulatory role of TRPC1 in SOC entry both in vascular smooth muscle and hepatocellular carcinoma cells." (PMID 27443843, 2016). "TRPC1 and TRPM7 were reported to be expressed in H4-IIE rat liver hepatoma cell lines, while TRPM2 channels were recently linked to APAP-induced oxidative stress and Ca2+ overload in mouse hepatocytes." (PMID 26903865, 2016).
hepatocellular carcinoma (continued). "Reciprocal alterations in the levels of TRPC1 and STIM1 have been observed, suggesting their interaction in regulating SOC entry in Huh7 hepatocellular carcinoma cells." (PMID 27443843, 2016). "In conclusion, this is the first study to systematically and comparatively analyze the contributions of redox-sensitive TRP channels such as TRPV1, TRPC1, TRPM2, and TRPM7 to human hepatoma cell death induced by APAP overdose." (PMID 26903865, 2016). "In different colorectal, thyroid, and hepatocellular cancer cells, TRPC1 did not contribute to cancer progression through SOCE." (PMID 35887266, 2022). "Furthermore, downregulation of TRPC1 significantly elevated SOC entry suggesting the regulatory role of TRPC1 both in A7r5 and Huh7 hepatocellular carcinoma cells." (PMID 27981039, 2016). "Therefore, this study seeks to determine which genes and pathways become deregulated upon TRPC1 silencing, to better understand the role of TRPC1 in SOC entry and hepatocellular carcinoma cell proliferation." (PMID 27443843, 2016). "TRPC1 silencing also suppresses Huh7 cell proliferation without affecting cell migration in real-time cellular analyses suggesting the role of TRPC1 in the regulation of hepatocellular carcinoma cell proliferation." (PMID 27981039, 2016).
Parkinson disease (11 papers, 2014 to 2025). A progressive degenerative disorder of the central nervous system characterized by loss of dopamine producing neurons in the substantia nigra and the presence of Lewy bodies in the substantia nigra and locus coeruleus. "TRPC1 knockout mice (TRPC1−/−) showed an increased unfolded protein response and loss of dopaminergic neurons in the substantia nigra, a condition closely resembling Parkinson's disease." (PMID 27034165, 2016). "Most interestingly, patients with Parkinson disease (PD), characterized by a loss of dopaminergic neurons in the substantia nigra, show decreased TRPC1 expression levels and higher levels of the unfolded protein in brain lysates." (PMID 25268281, 2014). "In a mouse model of Parkinson’s disease, TRPC1 overexpression prevents the development of the disease and these protective effects disappear in the TRPC1 knockout." (PMID 39000357, 2024). "In experimental models of Parkinson’s disease, the dopaminergic neurons of TRPC1-/- mice have increased rhythmic activity, leading to neurotoxicity and death." (PMID 39000357, 2024). "In neurodegenerative diseases like Huntington’s disease and Parkinson’s disease, TRPC1 protects neuronal cell death by reducing the Ca2+ influx." (PMID 39397856, 2024). "In neurodegenerative diseases like Huntington’s disease (HD) and Parkinson disease (PD), TRPC1 protects neuronal cell death by reducing the Ca2+ influx." (PMID 39397856, 2024). "In mouse models, the application of neurotoxins mimicking Parkinson’s disease (PD) leads to the downregulation of TRPC1 and store operated Ca2+ influx resulting in the death of dopaminergic neurons." (PMID 38300642, 2024). "A decrease in TRPC1 expression was observed in the neurotoxin-induced mouse Parkinson’s disease model." (PMID 33754657, 2021). "When neurotoxins mimicking Parkinson’s disease were introduced in DA neurons, TRPC1 expression was targeted, increasing activity of L-type Ca2+ channels and caspases, leading to neurodegeneration." (PMID 33328896, 2020). "For example, TRPC1 has been shown to maintain calcium homeostasis in a mouse model of Parkinson’s disease thus limiting neuronal degeneration." (PMID 32350291, 2020). "Furthermore, postmortem substania nigra samples from Parkinson’s disease individuals also showed decreased TRPC1 expression in the substantia nigra pars compacta region compared to non-Parkinson’s disease individuals." (PMID 33328896, 2020). "Further, application of the neurotoxin that mimics Parkinson’s disease, 1-methyl-4-phenyl-1,2,3,6-tetrahyrdro-pyridine (MPTP), led to increased activity of Cav1.3, and decreased expression of TRPC1 and inhibited thapsigargin mediated STIM1-Cav1.3 interactions." (PMID 35821821, 2022). "We predict that the deletion of TRPC1 will exert a more profound impact on cellular activity compared to knockouts of TRPC heteromers, especially in neurological conditions such as Huntington’s disease and Parkinson’s disease." (PMID 39397856, 2024).